SLC16A3 (solute carrier family 16 member 3)
Diseases named in the same sentence as SLC16A3 in open-access papers (continued):
Sharing a sentence is not in itself a finding about the gene and the disease.
cancer (54 papers, 2012 to 2025). A tumor composed of atypical neoplastic, often pleomorphic cells that invade other tissues. "Thirdly, although high expression of SLC16A3 is associated with poor clinical survival outcomes in cancer patients, it is still unclear how SLC16A3 affects patient clinical outcomes through the immune system and further research is needed." (PMID 40301866, 2025). "According to these results, SLC16A3 expression was noted to be strongly linked to the prognosis of diverse types of cancer, moreover, SLC16A3 exhibited remarkable accuracy (AUC > 0.9) in the prediction of BRCA, CHOL, ESCA, GBM, and KIRC." (PMID 40301866, 2025). "SLC16A3 has the potential to function as a biomarker for diagnostic and prognostic purposes in pan-cancer." (PMID 40301866, 2025). "Among the MCT family, MCT1 and MCT4 (encoded by SLC16A1 and SLC16A3, respectively) are most relevant in cancer, facilitating lactate metabolism and pH homeostasis." (PMID 40433363, 2025). "The outcomes revealed significant differences in SLC16A3 expression among distinct immune subtypes, implying its involvement in immune regulation and its potential as a diagnostic biomarker for human cancer." (PMID 40301866, 2025). "The Kaplan-Meier plots, univariate Cox regression, and the ROC curve were employed for assessing the prognostic and diagnostic significance of SLC16A3 in pan-cancer." (PMID 40301866, 2025). "SLC16A1 and SLC16A3 are overexpressed and associated with poor prognosis in cancers, such as pancreatic cancer." (PMID 35755805, 2022). "Multiple studies indicate that overexpression of SLC16A3 promotes the growth and proliferation of hypoxic cancer cells and is associated with poor cancer prognosis." (PMID 34093386, 2021). "The prognostic and diagnostic value of SLC16A3 in pan-cancer was then evaluated." (PMID 40301866, 2025). "Moreover, univariate Cox regression was utilized to confirm any potential association of SLC16A3 with the survival probability in diverse cancers." (PMID 40301866, 2025). "High expression of SLC16A3 has been related to elevated glycolytic metabolism in various cancers, which showed its potential as a prognostic marker associated with metabolic reprogramming of cancers." (PMID 39656344, 2024). "The expression data of SLC16A3 in human pan-cancer and healthy tissues were retrieved from various databases, including TCGA, GTEx, and TIMER2.0." (PMID 40301866, 2025). "The SLC16A3 expression was investigated in pan-cancer and the data acquired indicated that its expression exhibited remarkable variance across diverse malignant tissues." (PMID 40301866, 2025). "Gene Ontology and KEGG pathway analysis were employed to explore the function of SLC16A3 in pan-cancer." (PMID 40301866, 2025). "Although our research provides strong evidence for the potential role of SLC16A3 in the prognosis prediction and immunotherapy of many cancers, there are still certain limitations to this study." (PMID 40301866, 2025). "This study dealt with the exploration of SLC16A3 expression in human pan-cancer and its significance regarding disease prognosis." (PMID 40301866, 2025). "The resulting data demonstrated that SLC16A3 mRNA expression was overexpressed in most cancers and its protein expression was also high across diverse cancer types." (PMID 40301866, 2025). "Despite these findings, there has been a gap in research focusing on the expression profiles of SLC16A3 across diverse cancer types." (PMID 40301866, 2025). "Several studies have noted that SLC16A3 played a crucial role in the development of various cancers, including lung, prostate, colorectal, and pancreatic cancers." (PMID 40301866, 2025). "The Kaplan–Meier survival analysis results indicate a significant correlation between elevated SLC16A3 levels and unfavorable clinical outcomes in pan-cancer." (PMID 40301866, 2025). "Lastly, the investigation delved into the expression of SLC16A3 across various immune subtypes in human cancers." (PMID 40301866, 2025).
cancer (continued). "Central carbon metabolism in cancer-related genes, i.e., SLC16A3, FGFR3, LDHA, PGAM1, and SLC2A1, significantly reduced after treatment with CTPPPPD." (PMID 39275122, 2024). "Another study discovered a significant decrease in the expression of SLC16A3 following CTPPPPD administration, indicating that CTPPPPD is involved in cancer and is closely associated with the central carbon metabolism pathway in cancer." (PMID 39275122, 2024). "Even though there are far more types of acid-extruders than acid-loaders, piecewise knock-down of acid-extruders (SLC9A1, SLC4A7, or SLC16A3) can be sufficient to impair pHi control in cancer cells." (PMID 37999800, 2024). "SLC16A3, one of the lactate transport proteins, facilitates the transfer of lactate from cells to the extracellular space and is essential in the hypoxic cancer cells' proliferation and survival." (PMID 38779008, 2024). "To understand the mechanisms associated with the selected four SLCs, we performed GSEA to identify pathways enriched in cancers with high expression of SLC16A3, SLC53A1, SLC25A32, and SLC2A3." (PMID 39335197, 2024). "Lactic acid exporters SLC16A1 and SLC16A3 have also been suggested to play a role in intracellular alkalization in cancer." (PMID 35787947, 2023). "Cancer cells avoid this detrimental effect by promoting the efflux of lactic acid via the H+-coupled monocarboxylate transporters MCT1 (SLC16A1) and MCT4 (SLC16A3), both of which are upregulated in cancer." (PMID 36765717, 2023). "Further analysis revealed that co-culturing with cancer cells induced a major shift in CAF metabolism with increased expression of genes involved in glycolysis (SLC2A, GAPDH, LDHA, SLC16A3, ENO2, CA12), and the Hallmark gene set glycolysis." (PMID 37261365, 2023). "SLC16A3 is upregulated in several types of cancer and is responsible for the efflux of lactate from cancer cells." (PMID 37775731, 2023). "MCT1 (SLC16A1) is ubiquitously expressed and has high affinity for serum lactate as the cellular lactate importer, whereas MCT4 (SLC16A3) is strongly expressed in glycolytic cancer tissues for intracellular lactate export." (PMID 36615660, 2022). "During metabolic symbiosis, SLC16A1 is involved in the influx of lactic acid into oxidative cancer cells, while SLC16A3 is involved in the efflux of lactate from glycolytic cancer cells." (PMID 35755805, 2022). "SLC16A3 removes lactate produced by glycolysis from the plasma membrane and plays a key role in the growth and proliferation of hypoxic cancer cells." (PMID 35879749, 2022). "The significance of SLC16A3 in cancer has been preliminarily discussed, in terms of its role of mediating the transmembrane transport of various substances such as fatty acids and lactic acid." (PMID 35401672, 2022). "The most important gene found in cancer pathways through integrated analysis is SLC16A3, a monocarboxylate transporter." (PMID 35741360, 2022). "The upregulated status of SLC16A3 is particularly shown as a prognostic biomarker of cancer aversion; its upregulation in heat-stressed granulosa cells is notable." (PMID 35741360, 2022). "Regulation of SLC16A3 by DNA methylation and its prognostic value was reported in a previous pan-cancer study, including ESCA, HNSC, and LUSC." (PMID 34680330, 2021). "SLC16A3 participated in viral carcinogenesis and protein processing in the endoplasmic reticulum, indicating its important impact on cancer development." (PMID 32355273, 2020). "Cellular metabolism and transportation related genes (ALDOA, SLC16A3, TPI1, LDHB, KCNQ5, and PGM1), which are implicated in human cancer, also remained upregulated even 2-month after radiation exposure." (PMID 23216862, 2012). "In summary, this study indicated that SLC16A3 could serve as a potential marker for assessing prognosis and diagnosis in human pan-cancer." (PMID 40301866, 2025).
cancer (continued). "Moreover, the acquired data indicated that in pan-cancer, the SLC16A3 expression exhibited correlations with immune checkpoint genes and immune cells." (PMID 40301866, 2025). "As a result, a comprehensive study was conducted to elucidate the roles of SLC16A3 in pan-cancer." (PMID 40301866, 2025). "Consequently, a comprehensive study was designed to systematically explore the significance of SLC16A3 in pan-cancer scenarios." (PMID 40301866, 2025). "Finally, the involvement of SLC16A3 expression in the immune subtypes in human cancers was explored." (PMID 40301866, 2025). "Moreover, variations in SLC16A3 expression across different immune subtypes were observed in certain cancers." (PMID 40301866, 2025). "MCT1 (SLC16A1) and MCT4 (SLC16A3) are highly upregulated in cancers." (PMID 38339256, 2024). "SLC16A1 and SLC16A3, also known as SLC16A1/3, have considerable expression levels in cervical malignancies and are closely linked to the malignant characteristics of the cancer." (PMID 39229578, 2024). "Targeting SLC16A3 had gained attention as a potential therapeutic strategy in cancer treatment." (PMID 37775731, 2023). "Furthermore, MCT1 (SLC16A1) and MCT4 (SLC16A3) are ubiquitously expressed in the human body, with an obvious up-regulation observed in malignant tumors." (PMID 35646923, 2022). "Among the 14 MCT family members, MCTs 1 and 4 (SLC16A1 and SLC16A3, respectively), the most commonly upregulated isoforms in cancer, can either uptake lactate for energy purposes or export it to maintain homeostasis, and both have been linked to multidrug resistance as well as poor prognosis." (PMID 35011413, 2021). "MCT1 (SLC16A1) and MCT4 (SLC16A3) are important in cancer metabolism." (PMID 31201333, 2019). "MCT4/SLC16A3, which has the lowest affinity for lactate (Km 22-28 mM) but a high turnover rate, is well adapted to facilitate the export of lactate and protons by glycolytic cancer cells." (PMID 28107190, 2017). "MCT1 (SLC16A1) and MCT4 (SLC16A3) are the two isoforms most relevant for cancer physiology." (PMID 24409151, 2014). "Moreover, upregulated SLC16A3 expression was linked to poor OS and PFI of certain cancers." (PMID 40301866, 2025). "However, targeting SLC16A3 demonstrated potential for improving cancer therapy outcomes." (PMID 37775731, 2023). "Thus, SLC16A3 was believed to be a treatment site for glycolysis‐preference cancer cells." (PMID 33991070, 2021). "In addition, the expression of either SLC16A1 or SLC16A3 is up-regulated in the cancer tissues of all 14 cancer types except for COAD (see Materials and Methods for definition), which is known to have weak Warburg effect and hence generally not detected via PET/CT." (PMID 31071451, 2019). "Consequently, SLC16A3 it might be a possible target for cancer therapy." (PMID 40301866, 2025). "By contrast, under glucose shortage, uptake of lactate provides an essential advantage for those cancer cells expressing SLC16A1, which, in contrast to SLC16A3, also drives the import of lactate." (PMID 40508207, 2025). "The most relevant isoforms in cancer biology are MCT1 (SLC16A1), which is ubiquitously expressed and has high affinity for lactate and pyruvate, and MCT4 (SLC16A3)." (PMID 36353534, 2022). "In view of the pro-oncogenic role of these proteins, it is noteworthy, that G6PD, MAPK13, PNCK, SLC16A3, and SLC2A1 are among the candidate cancer genes identified by forward genetic screens in mice." (PMID 33427197, 2021). "Relative PAM, STC1, and HDAC4 expression were down-regulated, whereas CASP6, CHST6, SLC16A3, TPI1, KDELR3, VCAN, and CLDN9 were highly expressed in carcinoma tissues compared to the para-carcinoma tissues." (PMID 33424916, 2020). "Relevance of prognostic models for cancer-specific survival, comprising CD147 and MCT4 expression or SLC16A3 DNA methylation, was compared using chi-square statistics." (PMID 26384346, 2015).
cancer (continued). "In addition, further exploration of the biological function of SLC16A3 was performed via Gene Ontology and KEGG analyses in the context of pan-cancer." (PMID 40301866, 2025). "Interestingly, central carbon metabolism in cancer (HK2, MAPK3, MYC, PFKP, PKM2, SLC16A3), galactose metabolism (B4GALT2, HK2, PFKP) and fructose and mannose metabolism (HK2, PFKFB4, PFKP) are associated with metabolism." (PMID 39924557, 2025). "One popular model is that Na+/H+ exchangers, particularly NHE1 (SLC9A1), are the main reason for the reversal of pHi and pHe in cancer tissues, along with monocarboxylate-H+ efflux cotransporters MCT1 (SLC16A1) and MCT4 (SLC16A3) and carbonic anhydrases for CO2 hydration." (PMID 35787947, 2023). "The major MCT isoforms found in cancer cells are MCT1 (SLC16A1) and MCT4 (SLC16A3)." (PMID 33804674, 2021). "Within the favorable genes, UNC13B, and SFXN2 cover nine cancer types and in the same way, SLC2A1, PLS3, SLC16A1, and SLC16A3 within the unfavorable set of genes and could serve as novel target structures." (PMID 32599841, 2020). "Thus, proteolytic cleavage of the Ig-C2/Ig-I domain of BSG may lead to an altered conformation of the BSG/SLC16A3 and BSG/SLC16A1 conformation, supporting a forced export of lactate as a prerequisite for enhanced glycolysis and cancer cell growth." (PMID 40508207, 2025). "The results from our study showed that SLC16A1 and SLC16A3 RNA level expression was significantly increased in PAAD samples compared with normal tissues according to the Oncomine multiple pan-cancer analysis, indicating that these two genes widely participate in cancer biological behavior." (PMID 32355273, 2020). "However, no research has yet evaluated the significance of SLC16A3 in pan-cancer." (PMID 40301866, 2025).
infection (4 papers, 2010 to 2025). The state of being infected such as from the introduction of a foreign agent such as serum, vaccine, antigenic substance or organism. "Enrichment of populations of astrocytes that upregulate inflammatory‐responsive genes such as Pvalb and Slc16a3 was observed, while astrocyte populations enriched for homeostatic glutamate transporter genes, such as Slc1a2 and Slc1a3, decreased over the course of infection." (PMID 40635167, 2025). "RNA-seq showed infection at pH 7.4 decreased expression of SLC16A1 (MCT-1) 1.5 fold (p = 0.02) and increased SLC16A3 (MCT-4) 1.6 fold (p = 0.004)." (PMID 37418488, 2023).
bacterial infection (1 paper, 2021). "Bone marrow-derived neutrophils predominantly express SLC16A3 (MCT4) and have low levels of SLC16A1 (MCT1) and GPR81, with lipopolysaccharide (LPS) activation or bacterial infection increasing expression of SLC16A3." (PMID 34492096, 2021).
hematological cancer (1 paper, 2021). "Analysis of SLC16A1/SLC16A3 expression ratio in 205 hematological cancer cell lines, identified 44 cell lines, primarily of lymphoid origin, that are predicted to be sensitive to AZD3965." (PMID 34907165, 2021).
hematological malignancies (1 paper, 2021). "Our findings show that the combined expression of SLC16A1 (high) and SLC16A3 (low/no) may serve as an actionable biomarker for AZD3965 response in hematological malignancies." (PMID 34907165, 2021).
SLC16A3 also shares sentences with these, for which no sentence is quoted: gastric cancer (2 papers); adenocarcinoma (1); Arthritis (1); atherosclerosis (1); brain tumor (1); cervical cancer (1); cervical intraepithelial neoplasia (1); cholangiocarcinoma (1); clear cell renal cell carcinoma (1); depression (1); diffuse large B-cell lymphoma (1); endometrial cancer (1); female reproductive cancer (1); glycogenosis (1); Hepatitis (1); myopathy (1); oligodendroglioma (1); ovarian epithelial tumor (1); pleural mesothelioma (1); prostate carcinoma (1); rectum adenocarcinoma (1); renal cell carcinoma (1); skin cancer (1); uveal melanoma (1); viral infections (1).